IL6R (interleukin 6 receptor)
Diseases named in the same sentence as IL6R in open-access papers (continued):
Sharing a sentence is not in itself a finding about the gene and the disease.
tumor (continued). "Such a synergistic effect may be promoted by direct fusion to tumour-targeting antibodies rather than co-administration, thereby enhancing the accumulation of an IL-6R blocking entity in the tumour microenvironment." (PMID 36439165, 2022). "In particular, in PCa pSTAT-3 and IL-6R are present in 95% of metastatic niches of patients who die of castration-resistant PCa (CRPC); this suggests that in PCa, the activation of STAT-3 mediated by IL-6, IL-10 and EGF serves an important role for tumor progression and development of metastasis." (PMID 35703345, 2022). "Accordingly, we also detected the phosphorylation of NF-κB and the high expression of its downstream Cox-2 in tumor cells with TLR4 activation, suggesting that this signaling pathway still contributes to perpetuate proliferation signaling after cancer development, as observed by high levels of IL6R." (PMID 35327577, 2022). "Moreover, the most undifferentiated stem-like PC cells expressed the highest levels of IL-6 and IL-6R: blockade of JAK/STAT3 signaling could inhibit colony-forming and tumor initiation." (PMID 34830209, 2021). "Indeed, fat from KPC tumor mice had the lowest mean Ct for Il6, and skeletal muscle from KPC tumor mice had the lowest mean Ct for Il6r, implicating fat and muscle as the predominant sources of Il6 and Il6r in our model, respectively." (PMID 33851955, 2021). "Antibody blockade of IL6R inhibited tumor growth and metastasis in a TNBC mouse xenograft model, while IL7 blockade could prevent the accumulation of immune cells capable of promoting tumor growth." (PMID 33007869, 2020). "Among ADAM17 substrates, IL‐6R, TNFα, Notch1, and EGFR family ligands (e.g., TGFα, amphiregulin, epiregulin, and neuregulin‐1) promote the proliferation, survival, migration, and/or invasion of tumor cells (Zunke & Rose‐John, 2017), thus suggesting a prominent role for ADAM17 in cancer." (PMID 30833304, 2019). "However, although expression of Ccl5 and its receptors Ccr1 and Ccr3 were not affected by IL-6Rα deficiency in CAC, expression levels of Ccl20 and of its unique receptor Ccr6 were reduced in knockout tumours." (PMID 29695802, 2018). "Even if the bone-invasive tumor cells did not express IL6R, BMAs may still be able to induce these signaling cascades." (PMID 30013512, 2018). "The median survival of patients with tumors showing neither IL-6Rα expression nor STAT1 activity was 52 months shorter than in patient groups with tumor related IL-6Rα expression and/or STAT1 activity implying that presence of Stat1 and/or IL6Rα is beneficial for patient survival." (PMID 27191495, 2016). "Anti-IL-6R treatment could be investigated in these tumors as well, noting that anti-IL-6 was successfully used for this purpose in advanced renal cell carcinoma with documented IL-6 production by tumor cells." (PMID 39754984, 2025). "Thus, IL-6/IL-6R may suppress cell proliferation of CRC cells, especially in tumor buds." (PMID 38486225, 2024). "Notably, while IL-6 blockade promoted anti-tumor immunity in combination with anti-CTLA4, it ameliorated pathology driven by autoreactive Th17 responses, suggesting that IL-6/IL6R blockade may have the added benefit of attenuating immune-related adverse events." (PMID 36599350, 2023). "To explore whether IL-6 could mediate inter-clonal communication within a heterogeneous IBC tumor in vitro, we investigated whether supernatant from high IL-6-producing SUM149 cells could induce activation of the JAK-STAT3 signaling pathway and downstream effects in IL-6R positive SUM190 cells." (PMID 35565421, 2022). "Once binding to IL-6 receptor (IL-6R) and gp130 receptor, IL-6 could activate STAT3, mitogen-activated protein kinase (MAPK) and phosphatidylinositol 3-kinase (PI3K) pathways and increase tumor metastasis, indicating that IL-6 increasing metastasis is IL-6R/gp130 dependent." (PMID 26528698, 2015).
tumor (continued). "Blocking IL-6 or IL-6R did not decrease viability nor migration of the cancer cells, whereas inhibiting macrophage migration inhibitory factor (MIF) did decrease tumor cell migration, but not viability." (PMID 40061210, 2025). "Epigenetic modulations, including modification in DNA components and histones, telomer disruptions, expression of oncogenic and tumor suppressive microRNA (miR/miRNA), and non-long coding RNA, affect the regulation of IL6, IL6R, and its signaling." (PMID 39766086, 2024). "Interleukin 6 receptor staining, on the other hand, is abundant both in the non-tumoral epithelium surrounding OSCC and in tumor cells." (PMID 35327577, 2022). "In contrast, in 4T1/shIris1 tumors (Fig. 4e7), we observed a significant reduction in CK5 expression in tumor cells (Fig. 4e8 and 9` arrowheads), a complete absence of the CD90+ cells (Fig. 4e10 and 11` arrowheads), and the IL-6R+ cells (Fig. 4e12)." (PMID 31014367, 2019). "The expression pattern of all the factors (IL-6, IL-6R, gp130, and CD68) was not similar among the tumor tissues, such that all the factors were gradually up-regulated until five weeks." (PMID 26525581, 2015). "Given the apparent lack of IL-6/IL-6R expression in the OSA cells, we focused on OSM and its receptor in the fresh frozen OSA tumor samples from canine patients." (PMID 21481226, 2011). "In contrast to mRNA induction in muscle, there was no change in IL6R protein in the quadriceps; moreover, despite no mRNA induction, a significant increase of a 55-kD IL6R protein was observed in the adipose tissue of KPC tumor mice." (PMID 33851955, 2021). "However, downregulation of IL-6R by siRNA did not induce miR-34a expression in the HGSC cell line, A2780, suggesting that IL-6R/STAT3/miR-34a feedback is tumor specific." (PMID 31448054, 2019). "Because our results suggested that the IL-6 classical signaling, but not trans-signaling, may be related to the anti-tumor immune responses in NSCLC patients treated with ICIs, anti-IL-6 or anti-IL-6R Abs, but not sgp130 fusion proteins, may be promising to improve the efficacy of ICIs." (PMID 38469154, 2023). "Therefore, MCT-1 inhibition combined with IL-6R antagonist or miR-34a expression may further renovate non-BCSC effect and tumor-suppressive M1 macrophages in TNBC." (PMID 30885232, 2019).
cancer (253 papers, 2004 to 2025). A tumor composed of atypical neoplastic, often pleomorphic cells that invade other tissues. "Kaplan Meier survival analysis showed that in the full cohort, high IL6R expression trended towards an association with reduced cancer-specific survival (CSS) (HR = 1.472, 95%CI; 0.948–2.284, p = 0.082)." (PMID 39766336, 2024). "IL-6Rα expression is normally associated with hepatocytes and leukocytes but has also been described in cancer cells, including PDAC." (PMID 38141171, 2024). "Another report demonstrates that cancer-associated fibroblast-derived IL-6 increased c-Met expression in MET-unamplified GC cells through the IL-6/IL-6R/JAK2/STAT3 signalling pathway." (PMID 37950040, 2024). "We also found little evidence that several putative key inflammatory mediators in cancer development (e.g., epidermal growth factor, interleukin-6 receptor, interleukin-8) were associated with cancer risk." (PMID 38301482, 2024). "IL-6 or IL-6R genetic polymorphisms have been reported to be associated with risk or prognosis in patients with some cancers." (PMID 38469154, 2023). "It has been reported that IL-6 or IL-6R genetic polymorphisms are associated with risk or prognosis in patients with some cancers." (PMID 38469154, 2023). "They found that, following treatment with increasing doses of tocilizumab, only cancer cell lines expressing high levels of IL-6 and/or IL-6R were susceptible to tocilizumab-induced cell death." (PMID 36717545, 2023). "It has been reported that IL-6 (−634G>C) and IL-6R (48892A>C) genetic polymorphisms are associated with the risk or prognosis in patients with some cancers." (PMID 38469154, 2023). "Some of the defined target genes of LMNB1 like LIFR and IL6R are already reported to be cancer associated." (PMID 35883595, 2022). "Previous studies discovered that PTEN/Akt signaling pathway and IL-6R/JAK/STAT pathway are associated with carcinoma tumorigenesis." (PMID 33714953, 2021). "To accomplish this, we tested the therapeutic potential of Tocilizumab, an IL-6 receptor (IL-6R) blocker that inhibits IL-6 signaling implicated in both burn and cancer-induced WAT browning." (PMID 31740668, 2019). "Cytokine signaling via the interleukin-6 receptor (IL-6R) family and related receptors has been implicated in a number of cancers, including those with an ovarian origin." (PMID 29212170, 2017). "Dysregulated activity of A Disintegrin And Metalloproteinase 17 (ADAM17)/TNFα Converting Enzyme (TACE) is associated with inflammatory disorders and cancer progression by releasing regulatory membrane-tethered proteins like TNFα, IL6R and EGFR ligands." (PMID 27982031, 2016). "IL-6 signal cascade is triggered by IL-6/IL-6R complex via membrane-bound receptor and a soluble form of the IL-6R, which is frequently associated with inflammatory diseases and increased risk of cancers." (PMID 26745884, 2016). "DEN-induced inflammation stimulates the overexpression of IL-6, IL-6R, gp130 and other pro-tumorigenic cytokines, which in turn further aggravates inflammatory damage to the liver tissues and causes cancer." (PMID 27080032, 2016). "Among them, IL-6R, IL-8, IL-10RB, IL-12A, and IL-12B was significantly associated with the prognosis of cancer consistent to our finding." (PMID 25075970, 2014). "In the other types of cancer studies, IL-6R, IL-8, IL-10RB, IL-12A, and IL-12B genes were consistently associated with cancer prognosis between our study and theirs." (PMID 25075970, 2014). "The IL-6R, IL-8, IL-10RB, IL-12A, and IL-12B was associated with the prognosis of cancer in data of both our study and a previous study." (PMID 25075970, 2014). "Neither the evidence from tocilizumab trials nor the genetic studies to date have suggested an association of IL6R blockade with increased risk of cancer." (PMID 22421340, 2012).
cancer (continued). "To investigate whether AP neurons mediate the functions of IL-6 in the development of cancer cachexia, we sought to suppress Il6ra, the gene encoding IL-6Rα, in these neurons using a recently developed CRISPR/dCas9 interference system." (PMID 38824130, 2024). "In addition, the analyses of forty-five immune stimulators showed that METTL1 expression was positively related to TNFRSF18 as well as negatively associated with TNFSF15 and IL6R in nearly all cancers." (PMID 35432338, 2022). "In this study, we could show that the IL-6R cleavage was increased by the meprin β variant G45R in comparison to the wild-type enzyme, which could influence cancer and immune cell proliferation." (PMID 34692768, 2021). "In addition, IL-6R is one of the target genes of miR-21-5p, and secreted IL-6R (sIL-6R) is associated with metastasis and immunosuppression in most cancers." (PMID 33363013, 2020). "The pooled OR for development of any cancer was 0·42 (95% CI 0·06–2·88; four cases and 1196 controls) for tocilizumab treatment in randomised trials, and was 0·98 (95% CI 0·93–1·03; 5376 cases and 57 123 controls) for the IL6R rs7529229 variant." (PMID 22421340, 2012). "IL-6R signaling can promote stemness, growth and inflammatory responses in A549 cells and hence interventions like the IL-6R-blocking antibody tocilizumab have been used to investigate anti-cancer and anti-inflammatory effects on these cells." (PMID 41497628, 2025). "A 5-fluoro-2′-deoxyuridine (5-FUdR)-conjugated IL-6R aptamer induced cancer cell-specific cytotoxicity by inhibiting DNA synthesis and inducing apoptosis." (PMID 40277546, 2025). "Differential analysis between high-risk and low-risk cancer cells revealed that high-risk cancer cells exhibited elevated expression of genes associated with M2 macrophages, including CXCL2, IL6R, CXCL8, GDF15, CD68, and PTX3." (PMID 41034991, 2025). "The trans-signaling pathway mediated by soluble interleukin-6 receptor (IL-6R) plays a crucial role in the pathogenesis of chronic inflammatory diseases, autoimmune disorders, and various cancers." (PMID 41356664, 2025). "Here we show that CD109 plays a pivotal role as an essential regulator of IL6Rα expression and IL-6-driven oncogenic processes, enhancing cancer cell stemness and antioxidant capabilities in SCC cells." (PMID 40317079, 2025). "For instance, high IL-6 levels in cancer cells allow IL-6 receptor (IL-6R)-targeting aptamers to serve as delivery vehicles for chemotherapeutics." (PMID 40277546, 2025). "Next, we investigated the protein expression levels of the IL-6R/phosphorylated STAT3 (p-STAT3)/HLF/TFEB/PD-L1 axis in tissues from patients with cancer." (PMID 40779629, 2025). "Recently, a smart nanosystem of palladium nanoplates loaded with tocilizumab can selectively block IL-6R in the liver, ameliorating anemia with hepcidin production and suppressing cancer progression." (PMID 38890694, 2024). "miRNA modulates epigenetically and disrupts IL6, IL6R, and its pathway, and their role has been observed in various cancers." (PMID 39766086, 2024). "We furthermore show that IL-6 and M-CSF are strong drivers of increased abundance of immune incompetent CD14+ DC3s in the context of cancer and show that pharmacological inhibition of the IL-6R and CSF1R has potential to improve immunotherapy." (PMID 38242119, 2024). "Collectively, the generated NEF binders represent a promising class of new IL-6R protein antagonists that can be instrumentalized to achieve an efficient migrastatic anti-cancer treatment." (PMID 38715108, 2024). "IL6R inhibitors, particularly Tocilizumab, have shown promise in managing cancer and various chronic diseases." (PMID 39766086, 2024). "So far, therapeutic agents against IL‐6, IL‐6 receptor (IL‐6R), IL-6-sIL-6R complex, or IL-6 downstream signal transducers have been developed, and determined to be effective in the intervention of inflammatory diseases and cancers." (PMID 38890694, 2024).
cancer (continued). "Although IL-6/IL-6R-inhibiting compounds are in clinical development for various cancers, there is evidence that vaccination-based immunotherapy depends on IL-6 signaling in TAMs for optimal treatment efficacy." (PMID 39500527, 2024). "The use of tocilizumab against the interleukin-6 receptor (IL-6R) has been demonstrated as inhibiting the progression of diverse cancers in vitro and in vivo." (PMID 38256960, 2024). "This binding impedes the receptor’s interaction with the IL-6 ligand, highlighting the blockade of IL-6R as a promising therapeutic approach for cancers dependent on IL-6 signaling." (PMID 39101096, 2024). "All the studied genes involved in inflammation (MMP9, PTGS2, TNF-α, and IL-6R) were expressed by cancer cells." (PMID 39072314, 2024). "Then, IL-6 binds to IL-6R on the surface of cancer cells to induce STAT3 axis for cancer progression." (PMID 39014491, 2024). "The most prominent cytokines in our series, common to all cancers, are IL-6 and its soluble receptor IL-6Rα, TGFβ, IL-10, and G-CSF." (PMID 39114667, 2024). "There is an inverse relationship between miR-34a and IL6 levels in various cancers, leading to increased expression of IL6R mRNA and IL6/STAT3 signaling, as observed in OC, colorectal, and pancreatic cancer." (PMID 39766086, 2024). "IL-6R antagonism has also recently been shown to act synergistically with ICM blockers in cancer therapy." (PMID 37063842, 2023). "IL-6 signaling plays a crucial role in inflammation and cancer development, and several monoclonal antibodies targeting IL-6 or IL-6R have been developed as therapeutic agents for inflammatory diseases and cancers." (PMID 37759507, 2023). "Both IL-6R and IL-8R are known to be overexpressed in cancer, and IL-6R has been quantified around 103 receptors per cell in different carcinoma cell lines." (PMID 38187701, 2023). "Some of these molecules are targeted by the approved or experimental anti-cancer drugs (such as plerixafor for CXCR4 or tocilizumab for IL6R)." (PMID 37006265, 2023). "Given the extensive clinical experience with IL-6 inhibitors, and the pressing need to improve upon existing immunotherapies, combination of ICIs with approved anti-IL-6/IL6R agents warrants investigation in cancer patients." (PMID 36599350, 2023). "cGAS-STING drives the IL-6 dependent survival of chromosomally instable cancers through a chromosomal instability/cGAS-STING/Stat3 /RelB /NF-κB/Stat1/ILK-6/IL-6R/JNK /ASK /cell death pathway." (PMID 37854446, 2023). "Interleukin-6 receptor (IL-6R) plays an important role in inflammation, immune cell differentiation and cancer." (PMID 37664052, 2023). "According to the immunostimulatory and chemokine genes, CXCL12 is positively correlated with 20 cancers and IL6R is negatively correlated with 29 tumors." (PMID 37671947, 2023). "Secreted IL-6 binding to membrane IL-6R induces STAT3 expression which is aberrantly active in BCA to promote cancer proliferation and anti-apoptosis." (PMID 37480115, 2023). "Blockade of the IL-6/IL-6R signaling pathway has become a promising target for the therapy of cancers and inflammatory autoimmune diseases." (PMID 36419076, 2022). "SNHG12 recruits NF-κB to the IL-6R promoter, increasing IL-6R expression and promoting IL-6/miR-21 interaction between cancer cells and M2 macrophages, enhancing PD-L1 expression." (PMID 36612180, 2022). "Among the immunostimulatory factors, IL6R, TNFRSF18, TNFRSF25, and ULBP1 were significantly associated with RCC2 expression in the majority of cancer types." (PMID 36441563, 2022). "Targeting of IL-6 receptor (IL-6R) by small molecules is therefore an intensively studied strategy in cancer treatment." (PMID 36015338, 2022). "The JAK/STAT pathway plays a critical role in solid tumour progression and thus inhibition of downstream events by IL-6 or IL-6R blockage is a promising strategy for the development of new anti-cancer combination therapies." (PMID 36439165, 2022).